CX3CL1 (C-X3-C motif chemokine ligand 1)
Diseases named in the same sentence as CX3CL1 in open-access papers (continued):
Sharing a sentence is not in itself a finding about the gene and the disease.
lung fibrosis (continued). "Among eight serum cytokines, chemokines, and growth factors (IL-6, IL-8, IL-10, CCL2, CXCL10, CX3CL1, FGF-2, and VEGF), only IL-6 was found to be an independent predictor of the DLco decline in both SSc-ILD and idiopathic pulmonary fibrosis." (PMID 33105647, 2020). "We found significant correlations between serum concentrations of CX3CL1 and extent of baseline fibrosis on HRCT (r = 0.2, p = 0.039), as well as significant lung fibrosis >10%." (PMID 30457999, 2018). "Although anti-CX3CL1 mAb therapy did not attenuate lung fibrosis in SKG-ILD, the infiltration of BALF M1 macrophages strongly expressing CX3CR1 into the lungs was efficiently suppressed." (PMID 34067842, 2021). "A treatment with anti-CX3CL1 mAb suppressed the infiltration of M1 macrophages, but not M2 macrophages, into the alveolar space, but did not attenuate lung fibrosis, suggesting the potential of CX3CL1 to regulate macrophage infiltration in SKG-ILD." (PMID 34067842, 2021). "No significant changes were observed in lung fibrosis or the number of BALF cells by the treatment with anti-CX3CL1 mAb." (PMID 34067842, 2021). "In the present study, anti-CX3CL1 mAb successfully inhibited the migration of M1 macrophages, but failed to suppress the migration and/or polarization of M2 macrophages; therefore, it did not exert therapeutic effects against lung fibrosis with CX3CL1 blockade alone." (PMID 34067842, 2021). "Anti-CX3CL1 mAb therapy efficiently suppressed the infiltration of BALF M1 macrophages in the mouse model of RA-ILD, and therefore, this therapy combined with anti-fibrotic drugs may have a more robust therapeutic effect on lung fibrosis." (PMID 34067842, 2021). "Although anti-CX3CL1 mAb alone did not exert therapeutic effects against lung fibrosis, its combination therapy with anti-fibrotic drugs, such as nintedanib or pirfenidone, may be expected to have a therapeutic effect on ILD." (PMID 34067842, 2021). "Thus, the role of CX3CL1 in lung fibrosis resolution may not be limited to the recruitment of macrophages but may involve other immune cells, including NK cells." (PMID 33688918, 2021).
osteoarthritis (14 papers, 2014 to 2025). A noninflammatory degenerative joint disease occurring chiefly in older persons, characterized by degeneration of the articular cartilage, hypertrophy of bone at the margins and changes in the synovial membrane. "In research on degenerative joint disease-related pain in cats, CX3CL1 levels were found to be upregulated in both the dorsal root ganglia affected by the disease and the spinal cord in cats displaying clinical signs of OA pain, compared to those without." (PMID 38274820, 2023). "Previous studies have demonstrated that the CX3CL1/CX3CR1 axis is involved in cartilage destruction due to osteoarthritis by inducing MMP-3 secretion from synovial fibroblasts through c-Raf, MEK, ERK, and NF-κB pathways." (PMID 38283363, 2023). "We investigated the signaling pathway involved in CX3CL1-induced MMP-3 production in osteoarthritis synovial fibroblasts (OASFs)." (PMID 29268768, 2017). "Within the pathologies of the musculoskeletal system, the role of the CX3CL1/CX3CR1 axis was to date associated with development of conditions that include, but are not limited to, osteoarthritis (OA), rheumatoid arthritis (OA), and degenerative disc disease (DDD)." (PMID 32884948, 2020).
tauopathy (14 papers, 2014 to 2025). Neurodegenerative disorders involving deposition of abnormal tau protein isoforms (tau proteins) in neurons and glial cells in the brain. "Lastly, overexpression of CX3CL1 in the PS19 model of tauopathy, reduces synaptic and neuronal loss and improves memory and cognition." (PMID 35764973, 2022). "To understand whether neuroinflammation is associated with changes in CX3CL1 expression, we examined CX3CL1-immunopositive cells in the substantia nigra in synucleinopathy and tauopathy cases." (PMID 40842561, 2025). "CX3CL1 expression is decreased in neurons while endothelial CX3CL1 expression is upregulated in the substantia nigra of subjects with a synucleinopathy or tauopathy." (PMID 40842561, 2025). "Using the cerebrospinal fluid to distribute CX3CL1 through the CNS, the authors found that the elevation of CX3CL1 levels improved cognitive functioning in the same tauopathy model." (PMID 39940727, 2025). "Conversely, the CX3CL1 expression in endothelial cells was significantly increased in subjects with synucleinopathy or tauopathy." (PMID 40842561, 2025). "Altered CX3CL1/CX3CR1 signaling has been demonstrated to regulate the pathological changes in both animal models of tauopathies and AD patients." (PMID 33672982, 2021). "We have observed elevated levels of CX3CL1 in the hTau mouse model of tauopathy at the time of early stage tau pathology." (PMID 26089772, 2015). "In a recent study, adeno-associated virus (AAV)-mediated expression of only the soluble form of CX3CL1 resulted in reduced microglial activation and tau pathology in the rTg4510 mouse model of tauopathy." (PMID 26089772, 2015). "Whether CX3CL1 expression is changed in nigral endothelial cells with synucleinopathy and tauopathy is unknown." (PMID 40842561, 2025). "As PD and MMD-LB are synucleinopathies, whether CX3CL1 downregulation also occurs in the brains with tauopathies was unclear." (PMID 40842561, 2025). "As PD is primarily a synucleinopathy and PSP a tauopathy, we also compared the alterations in CX3CL1, microglia, and CD4+ T cells in both neurodegenerative diseases to determine whether there is a difference between pathologies." (PMID 40842561, 2025). "The NLRP3 inflammasome, the autophagy-lysosomal pathway, CX3CL1 signaling pathway, and ApoE4 are all therapeutic targets that could yield potential new treatments for tauopathies." (PMID 33672982, 2021). "The present study seeks to determine if genetically expressing only the soluble chemokine domain of CX3CL1 could prevent tau pathology in both chemical (LPS) and genetic (hTau) mouse models of tauopathy." (PMID 30253780, 2018). "The alterations of CX3CL1, TMEM119, and CD4 in subjects with tauopathy also displayed a similar pattern of inflammatory changes." (PMID 40842561, 2025). "The protective role of Cx3cl1/Cx3cr1 is also seen in models of AD (APPPS1 and R1.40), ALS (TgSOD1G93A), tauopathy and PD." (PMID 24655482, 2014).
Arthritis (13 papers, 2011 to 2024). Inflammation of a joint. "Several of these genes, including phospholipase A2, kallikrein, IL-18, and CX3CL1, have been associated with arthritis or inflammatory pain." (PMID 21689431, 2011). "Given the role of the CX3CL1/CX3XR1 axis in arthritis, other studies investigate its involvement in HA." (PMID 39337384, 2024). "We previously demonstrated that the blockade of CX3CL1 efficiently suppressed collagen-induced arthritis in mice." (PMID 34067842, 2021). "(J) Synovial fibroblasts obtained from WT mice with arthritis were incubated with sFasL or sTRAIL and CX3CL1 levels were measured using ELISA." (PMID 34223817, 2021). "As one example, Iwamoto and co-workers have described the increased expression of six CC chemokines, five CXC chemokines, XCL1, and CX3CL1 in the synovial tissues of rheumatoid arthritis patients, compared to other forms of arthritis or healthy controls." (PMID 28178200, 2017). "A microarray assay using joint tissues from mice with arthritis implied that the chemokine CX3CL1 may play an important downstream role of the interaction." (PMID 34223817, 2021). "Five of the 13 chemokines that decreased in the whole group decreased in the 7 children with arthritis as well, and three of those chemokines were the ones for which decreases remained significant after adjustment for multiple comparisons: CX3CL1, SCF and IL-10RB." (PMID 34112181, 2021). "Additionally, mice deficient for the Gpsm3 gene were protected from arthritis induced by anticollagen antibodies that reduced CCL2 and CX3CL1-mediated migration of myeloid cells." (PMID 30648118, 2018). "(D) Cx3cl1 expression in CD45+ immune and CD45– non–immune cells from the joints of WT mice with arthritis after sFasL treatment." (PMID 34223817, 2021). "Taken together, the effects of CX3CL1, MMP-10, and Flt3L can be diverse, and it may depend on the immunological context if a decrease or increase in their level is more favorable in arthritis." (PMID 36124688, 2022). "We then analyzed the expression of corresponding ligands and found a decrease of CX3CL1 expression particularly in PBM and TMT, while the expression of CCL2 was significantly increased in both medullary and extramedullary tissues of mice with arthritis in comparison to control." (PMID 34925336, 2021).
Insulin resistance (13 papers, 2012 to 2025). Increased resistance towards insulin, that is, diminished effectiveness of insulin in reducing blood glucose levels. "In GDM, higher levels of CX3CL1/CX3CR1 in the placenta are linked to increased insulin resistance (IR) and an inflammatory response." (PMID 37928902, 2023). "Furthermore, since CX3CL1 levels in the blood are linked to indicators of insulin resistance in people with GDM, researchers investigated whether resveratrol therapy might reduce CX3CL1/CX3CR1 production." (PMID 37928902, 2023). "However, CX3CL1 administration in vivo has been reported to have a contradictory effect in diminishing glucose intolerance and insulin resistance." (PMID 34948325, 2021). "Since FCH is associated with a high risk of cardiovascular disease, the objective of the present study was to assess the presence of alterations in the CX3CL1/CX3CR1 axis in patients with FCH and to evaluate the influence of insulin resistance (IR) and sex." (PMID 41153665, 2025).
lung adenocarcinoma (13 papers, 2016 to 2025). A carcinoma that arises from the lung and is characterized by the presence of malignant glandular epithelial cells. "In an analysis of seven expression datasets, CX3CL1 expression was a strong and reproducible positive prognostic marker in lung adenocarcinoma." (PMID 38866964, 2024). "Increased mRNA expression of CX3CL1 has been reported as a positive prognostic factor in patients with lung adenocarcinoma." (PMID 37315289, 2023). "CX3CL1 was downregulated in lung adenocarcinoma (LUAD) tumors compared to normal lung tissues in TCGA cohorts, indicating tumor immune evasion." (PMID 36869384, 2023). "Here, we showed that CX3CL1 can further invasion and migration of lung adenocarcinoma A549 and lung squamous cell carcinoma H520." (PMID 33191645, 2021). "The current study demonstrates that CX3CL1 promotes the phosphorylation of cortactin via c‐Src and c‐Abl signalling pathways, and further promotes the migration and invasion of lung adenocarcinoma A549 cells and lung squamous cell carcinoma H520 cells." (PMID 33191645, 2021). "Intriguingly, tumor tissues of bladder urothelial carcinoma (BLCA), breast invasive carcinoma (BRCA), kidney chromophobe (KICH), lung adenocarcinoma (LUAD), lung squamous cell carcinoma (LUSC), and prostate adenocarcinoma (PRAD) express CX3CL1 at significantly lower levels than normal tissues." (PMID 37153002, 2023). "We also found the substantial expression of several chemokines (CXCL1, CXCL5, CXCL8, and CX3CL1) related to cell migration, invasion, metastasis, or EMT, in KRAS-mutant lung adenocarcinoma cell lines, which was also dependent on MAPK signaling (unpublished data)." (PMID 27846317, 2016). "In another report, high CX3CL1 level was a poor prognostic factor in lung adenocarcinoma patients with a history of smoking, but not in lung adenocarcinoma patients without a history of smoking or in lung squamous cell carcinoma patients with a history of smoking." (PMID 40508161, 2025). "Furthermore, a pooled analysis based on survival analysis of lung adenocarcinoma patients showed that high CX3CL1 levels were a predictor of good prognosis, but not a significant prognostic factor in squamous cell lung cancer." (PMID 40508161, 2025).
renal fibrosis (13 papers, 2019 to 2025). A final common manifestation of a wide variety of chronic kidney diseases characterized by glomerulosclerosis and tubulointerstitial fibrosis. "Anti-inflammation (downregulation of CX3CL1, reduction in CD68+ macrophages infiltration) and decreased renal fibrosis (reduction of α-SMA).Downregulated CX3CL1 was associated with specific miRNAs in EVs (miR-15a, miR-15b, mi-R16)." (PMID 35359949, 2022). "Other miRNAs, including miR-16, miR-15a and miR-15b in MSCs-derived extracellular vesicles, can alleviate renal inflammation and inhibit renal fibrosis by suppressing the expression of CX3CL1." (PMID 35902973, 2022). "Although previous studies have demonstrated that CX3CL1 is involved in cardiac and renal fibrosis, our current findings have identified a novel CX3CL1 signaling pathway related to the progression of fibrosis." (PMID 35370759, 2022). "Therefore, it is debatable whether the CX3CL1/CX3CR1 axis contributes to renal fibrosis." (PMID 40508161, 2025). "Furthermore, human cortical fibroblast cell lines also express CX3CR1 and migrate towards the CX3CL1 in dose-dependent manner, suggesting a functional role for CX3CL1/CX3CR1 in promoting renal fibrosis through fibroblast recruitment." (PMID 40508161, 2025). "Overall, these data from animal model studies are consistent with a mechanism by which intra-renal induction of CX3CL1 expression following IRI plays a key role in monocyte-derived macrophage infiltration of the renal parenchyma and in the subsequent severity of renal fibrosis." (PMID 34163473, 2021). "They regulate multiple signaling pathways such as Wnt/β-catenin, TGF-β1/Smad, Akt/mTOR, CX3CL1-RAF/MEK/ERK, mTORC1/p70S6K, SIRT1-NF-κB, and interfere with different cytokine or inflammatory factors expression to regulate the development and progression of renal fibrosis." (PMID 36160409, 2022).
systemic lupus erythematosus (13 papers, 2015 to 2025). An autoimmune multi-organ disease typically associated with vasculopathy and autoantibody production. "In inflammation and specifically lupus, the literature displays contradictory evidence for the functions of CX3CL1/CX3CR1 interactions." (PMID 38299151, 2023). "The chemokines CCL2, CCL3, CCL5, CXCL10, CXCL12, CXCL13, and CX3CL1 are expressed in the nephritic kidney of lupus-prone mice and SLE patients and increase inflammatory cell infiltration into the kidney." (PMID 30057623, 2018). "In MRL/lpr mice, CD16+ cells in glomeruli are increased with lupus development, with increased protein level of CX3CL1 detectable in glomeruli, interstitial microvasculature, and arterial regions." (PMID 27403037, 2016). "Additional targets, such as the CSF-1 receptor kinase or CX3CL1, lead to macrophage depletion and greatly improved kidney pathologies in mouse models of nephritic lupus." (PMID 26997761, 2016). "However, studies reported that an antagonist of CX3CL1 delayed the onset and slowed the progression of lupus nephritis in MRL/lpr mice, suggesting a detrimental role for CX3CL1/CX3CR1 interaction in lupus." (PMID 38299151, 2023). "Elevated expression of CX3CL1 has been obtained in different vasculitic and autoimmune disorders like RA and systemic lupus erythematosus (SLE), possibly playing a role in neuropsychiatric manifestations and synovitis." (PMID 39392260, 2024). "While reports on ANCA-associated glomerulonephritis are lacking, both CX3CL1 and monocytes expressing CX3CR1 are known to be elevated in systemic lupus erythematosus." (PMID 34009468, 2021). "Unlike MRL/lpr mice, CX3CR1 and CX3CL1 expression in the kidney of NZB/W F1 mice do not change with lupus progression, suggesting differences between various lupus-prone mouse models." (PMID 27403037, 2016). "Therefore, in the context of lupus, the absence of CX3CL1/CX3CR1 interaction may facilitate migration of Gr1+ inflammatory monocytes to the kidney, causing injury." (PMID 38299151, 2023).
asthma (12 papers, 2012 to 2024). "Among them, C3, PTGIR, CX3CL1, and PTHLH has important clinical diagnostic value and are correlated with infiltration of multiple immune cell types in asthma." (PMID 38640283, 2024). "C3, PTGIR, CX3CL1, and PTHLH have important clinical diagnostic values and are correlated with infiltration of multiple immune cell types in asthma." (PMID 38640283, 2024). "Among them, 4 genes validated by ROC curve analysis with AUC > 0.70 revealed potential diagnostic values for asthma, including C3, PTGIR, CX3CL1 and PTHLH." (PMID 38640283, 2024). "Interestingly, genes previously associated with asthma, such as CCL5 (RANTES), CXCL10 (IP10), LGALS9, CX3CL1, C5AR1, and CDHR3 fall into these three different groups." (PMID 25706956, 2015). "Interestingly, the changes in expression of lectin galactoside-binding soluble 9 (LGALS9), chemokine (C-X3-C motif) ligand 1 (CX3CL1) and complement component 5a receptor 1 (C5AR1) have been previously reported to be associated with asthma." (PMID 25706956, 2015). "Mediators associated with anti-viral immune responses to rhinovirus may perhaps be extended to include fractalkine/CX3CL1, a unique dual soluble chemokine and adhesion factor, contributing further to our understanding of defective rhinovirus-induced anti-viral responses in asthma." (PMID 28859129, 2017). "To further validate our findings, we analyzed the correlation between 4 hub genes (C3, PTGIR, CX3CL1, and PTHLH) and immune cell infiltration in asthma, This result indicates that C3, PTGIR, CX3CL1, and PTHLH expression were significantly correlated with the infiltration of immune cells." (PMID 38640283, 2024).
type 2 diabetes (12 papers, 2011 to 2024). "Each SD increase in TGF-alpha (OR = 1.16, 95% CI = 1.15-1.17, P-value = 3.33e-248) and CX3CL1 (OR = 1.30, 95% CI = 1.04-1.63, P-value = 0.0199) was associated with an increased risk of developing type 2 diabetes." (PMID 38606083, 2024). "The adipokine C-X3-C motif chemokine ligand 1 (CX3CL1, Fractalkine) and interleukin-18 (IL-18) both are associated with type 2 diabetes and are increased in the plasma of respective patients." (PMID 34281240, 2021). "In conclusion, our study revealed pivotal contributions of TGF-alpha, FGF-21, hGDNF, and CX3CL1 in the advancement of type 2 diabetes and its complications." (PMID 38606083, 2024). "In addition, plasma CX3CL1 levels are augmented in individuals with type-2 diabetes." (PMID 30245615, 2018). "Our findings indicated that TGF-α and CX3CL1 exhibited a positive correlation with the genetically predicted susceptibility to T2D, and elevated concentration of FGF-21 and hGDNF could mitigate the risk of developing T2D, while type 2 diabetes did not exert a significant influence on them." (PMID 38606083, 2024).
amyotrophic lateral sclerosis (11 papers, 2012 to 2023). Amyotrophic lateral sclerosis (ALS) is a neurodegenerative disease characterized by progressive muscular paralysis reflecting degeneration of motor neurons in the primary motor cortex, corticospinal tracts, brainstem and spinal cord. "Exogenous CX3CL1 is neuro-protective in some models of neuro-inflammation, and disruption of CX3CL1 signaling causes neurotoxicity in models of systemic inflammation, PD, and amyotrophic lateral sclerosis but protects against neuronal loss in a mouse model of focal cerebral ischemia." (PMID 25635231, 2014). "In an amyotrophic lateral sclerosis model, lack of CX3CL1/CX3CR1 signal in the CNS activates the NF-κB pathway, with increased microglia activation and neuronal damage." (PMID 37234914, 2023). "An in vivo study reported significantly increased CX3CL1 expression in motor neurons in the anterior horn of the spinal cord in SOD1G93A mice, which is a model of amyotrophic lateral sclerosis (ALS), at 40 days; however, it decreased at 90 and 120 days due to motor neurons loss in the anterior horn." (PMID 34594188, 2021).